TLR2 (toll like receptor 2)
Diseases named in the same sentence as TLR2 in open-access papers (continued):
Sharing a sentence is not in itself a finding about the gene and the disease.
infection (continued). "This could not be explained by impaired bacterial clearance as TLR2-deficient mice cleared the infection similar to controls." (PMID 21695078, 2011). "Furthermore, reduced Treg numbers in TLR2−/− mice, allowed these mice to be sensitized even at day 10 after infection, extending the time window for antigen sensitization relative to the initial infection." (PMID 21695198, 2011). "Although there is evidence that TLR-2 may play a regulatory role during infection with L. braziliensis and downregulate DC IL-12 production, all other studies implicate TLRs and TLR-4 ligation and MyD88 signalling in particular in the generation of protection against infection." (PMID 21664694, 2011). "However, AdVαT2ib infection resulted in abrogation of TLR2 cell surface expression." (PMID 20388199, 2010). "Another intriguing possibility is that TLR2-mycoplasma interactions on antigen presenting cells, such as dendritic cells and macrophages, and other immune cells may also modulate the types of adaptive immune responses generated in response to infection." (PMID 20505832, 2010). "Thus the roles of TLR2 in innate responses to SA are context dependent, and may include detrimental roles in infection outcome." (PMID 20404927, 2010). "Louse infection grade showed highly significant negative association with TLR2 responses to HKLM (LMM, F1,81.1 = 18.90; P < 0.001) and zymosan (LMM, F1,75.0 = 9.54; P = 0.003), TLR9 response (LMM, F1,80.6 = 7.20; P = 0.009) and TIR (LMM, F1,80.7 = 17.03; P < 0.001)." (PMID 19386086, 2009). "Nevertheless, high upregulation following infection of both TLR2 and TLR13 in astrocytes and their foot processes that terminate at blood vessels may provide necessary signals for initiation of infiltration of immune cells to the CNS and the subsequent adaptive immune response." (PMID 19077284, 2008). "Indeed, infection with helminths predicted low expression of TLR2 and, to a lesser extent, of TLR4." (PMID 18414649, 2008). "A limited role for TLR2 during infection with WT S. pneumoniae is further supported by a recent study in which intact pneumococci were administered intraperitoneally, although TLR2 KO mice displayed a modestly slower clearance of S. pneumoniae from their nasopharynx in another investigation." (PMID 17711480, 2008). "Thus, induction of lower expression of TLR2 by infection with schistosomes seems to be specific." (PMID 18414649, 2008). "In addition, TLR2 deficiency did not influence the expression of TLR4 on lung macrophages or blood monocytes or granulocytes throughout the infection." (PMID 17676990, 2007). "Interestingly, even though its activation is delayed, among the three MyD88 is the most important molecule for host defense against Brucella infection in vivo, since MyD88 knockout (KO) mice are more susceptible to infection when compared to TLR4, TLR2, TLR4/TLR2 KO mice." (PMID 16556309, 2006). "Since TLR2 is involved in Chlamydia-induced TGF-beta, an anti-inflammatory cytokine with an important role in fibrosis, and thus very likely in post-infection tubal pathology, it might explain why CD14 polymorphisms may not severely impact the development of tubal pathology." (PMID 16368002, 2005). "Once produced, IL-37 attenuated TLR2, TLR4 and NOD1-mediated activation and TLR-mediated IL-8 responses to H. pylori infection." (PMID 41689434, 2026). "PPE18 is required by Mtb to establish an effective infection in vivo, impairing MHC-II antigen presentation and interacting with TLR-2 to inhibit pro-inflammatory responses." (PMID 40787981, 2025). "At two weeks post-infection, serum IFN-γ levels were higher in the TLR2-vaccine and BCG groups than in the control group, although variability was greater in the TLR2-vaccine group." (PMID 41346624, 2025). "Gene expression of interleukin (IL)-6, IL-8, TLR2, TLR4, IL-1 alpha (IL-1α), and CXCR1 was evaluated by quantitative real-time polymerase chain reaction at 0, 6, 12, 24, 48, and 72 h post-infection." (PMID 40453956, 2025).
infection (continued). "TLR2 and TLR4 exhibit strong co-expression, suggesting coordinated regulation during udder infection." (PMID 40453956, 2025). "For example, the costimulation of TLR2 and TLR4 in macrophages synergistically increases the production of proinflammatory cytokines, amplifying the overall immune response to infections." (PMID 41295183, 2025). "E protein is a ligand for Toll-like receptor 2 (TLR-2) and activates the NOD-like receptor (NLR) family pyrin domain-containing 3 (NLRP3) inflammasome pathway during infection." (PMID 40573459, 2025). "In the present study, the TLR2 expression levels of the mouse microglia cell line BV2 cells infected with UV strain, HV+ strains, and P1/7 were compared at 4 h and 8 h post-infection." (PMID 40574283, 2025). "We also found upregulation of TLR2/4 and IRF7 relative to uninfected cells, and these were also enhanced during Mcat mono-infection and coinfection." (PMID 40492732, 2025). "This differential regulation by TLR2 and TLR4 highlights the complex interplay between host receptors during infection." (PMID 40821830, 2025). "In conclusion, although this meta-analysis did not reveal a consistent overall association between TLR2 rs3804099 or del −196 to −174 polymorphisms and H. pylori susceptibility, the results suggest that these variants may influence infection risk in specific genetic or bacterial contexts." (PMID 41503064, 2025). "Our results revealed a significant parabolic increase in TLR2, TLR4, TLR7, and TLR10 expression following infection, with TLR2—the primary receptor for S. aureus recognition—showing the most pronounced response." (PMID 41305370, 2025). "Our results show that calf tracheal tissues revealed significantly elevated expression levels of TLR2, TLR4, TLR7, and TLR10, as well as MyD88 after infection with M. bovis, and initiated the innate immunity Toll-like receptor signaling pathway." (PMID 40005807, 2025). "TLRs, especially TLR2 and TLR4, significantly affect post-infection and lipopolysaccharide-mediated regulation of gastrointestinal motility." (PMID 39749341, 2024). "Here, we observed higher TLR2, TLR4, TLR5, TLR6, TLR8, TLR9, Myd88, NLRP3, ASC, and TNF-α mRNA expression at seven weeks after infection by S. mansoni in BALB/c and C57BL/6 mice compared to Swiss mice." (PMID 38896633, 2024). "TLR2 and TLR4 represent some of the initial immune responses employed by the host to combat infections, serving a crucial function in identifying pathogens." (PMID 39749340, 2024). "The probiotics induced the expression of immune-related genes such as IL-8, IL-1β, TNF-α, TLR-2, C3, IFN-γ, and MHC I. Additionally, these treatments increased the survival rates of grey mullet following infection with N. seriolae." (PMID 39563419, 2024). "In undernutrition 65% + infection group, PD-1 (P = 0.0364), PD-L1 (P = 0.0481) and Bax (P = 0.0394) were conversely upregulated, and ICOS (P = 0.0274), TLR2 (P = 0.0097) and TLR4 (P = 0.0361) were also upregulated." (PMID 38185681, 2024). "Leendertse and colleagues firstly discovered that MyD88, at least in part through Toll-like receptor 2 (TLR2), is essential for the effective clearance of E. faecium during peritonitis by facilitating neutrophil recruitment to the infection site." (PMID 38951957, 2024). "All of this is consistent with previous reports showing that lincRNA-Cox2 is overexpressed in a MyD88-dependent manner in response to the activation of various TLRs such as TLR2, TLR4, TLR7/8, or in response to infection with Listeria monocytogenes." (PMID 38464511, 2024). "Moreover, EgP stimulates the TLR2/MyD88/NF-κB signaling pathway, resulting in the synthesis of α-SMA and Collagen I. The data suggest that infection with E. granulosus may stimulate the production of IL-9 through the activation of the TLR2/MyD88/NF-κB signaling pathway, which is mediated by TLR2." (PMID 39199394, 2024). "NK cells eliminated infections by overexpressing NKp46, NKp30, and NKG2D on NK cells when TLR2 was activated." (PMID 38685971, 2024).
infection (continued). "Virus itself can express Micro RNA s during human infection, as miR-UL112-3p has been demonstrated as a human TLR2 downregulator that inhibits the downstream cascade of reactions, to evade the antiviral immune responses." (PMID 39729468, 2024). "The mixture of various probiotics and Bifidobacterium with galactooligosaccharides and fructo-oligosaccharides has a defensive effect against infections, aggregating the production of TNF-α, IL-4, IFN-γ and TLR2 expression." (PMID 39608222, 2024). "Like TLR2, the level of TLR4 was significantly increased with increasing time points post infection." (PMID 36707891, 2023). "Early recognition of F. tularensis by TLR2 and MYD88 contributes to host protection during both macrophage and in vivo infection, with MYD88 playing a more critical role in vivo." (PMID 37404047, 2023). "TLR2 and its adapter protein MYD88 localize to the chlamydial inclusion during infection suggesting the ligand is sampled within the inclusion during infection." (PMID 37662000, 2023). "We observed increasing mb-TLR2 expression in NK cells and decreasing CD4+ T cells in the jejunum following infection." (PMID 38140264, 2023). "While the TLR2−/− mice exhibited a faster time to death upon infection with the WT LVS, the TLR2−/− mice were still able to control and survive infection with the ∆tolC mutant." (PMID 37404047, 2023). "Fc receptors (FcαR, FcyR), Toll-like receptor TLR2 and cell surface receptor and differentiation marker CD14 were exclusively overproduced in the presence of hSAA-1 and downregulated (FcyR, TLR2, TLR4, CD14) during infection." (PMID 37781389, 2023). "Our data demonstrate that F. tularensis suppresses TLR2- and MYD88-dependent activation of p38 early during infection in a TolC-dependent manner." (PMID 37404047, 2023). "During Leishmania infection, the participation of TLR-9, TLR-4, TLR-2, and TLR-3 is pivotal for mediating a proinflammatory cytokine response and subsequent infection control." (PMID 37111420, 2023). "Not like bacterial infections, virus itself can express Micro RNA s during human infection, for instance, miR-UL112-3p has been demonstrated as a human TLR2 downregulator." (PMID 38014008, 2023). "We also observed an increase in membrane-bound TLR2 (mb-TLR2) in cytotoxic T cells, B cells, and NK cells in PBMC and NK cells in the gut after infection." (PMID 38140264, 2023). "In this experiment, following the infection of Balb/c mice with M. pneumoniae or stimulation of mouse macrophages RAW264.7 with LAMPs, a noticeable increase was observed in TLR2 protein expression in mouse lung tissues and RAW264.7 cells." (PMID 37894556, 2023). "To explore the existence of TLR-TLR crosstalk, we therefore treated wildtype and Tlr4−/− iBMDMs with inhibitors of TLR2 (CU CPT22), TLR3 (TLR3/dsRNA complex inhibitor), and TLR9 prior to infection with C. neoformans." (PMID 37580395, 2023). "The TLR2 gene transcription levels in primary astrocytes and BV2 cells infected with NN1 peaked at 4 h post-infection, whereas the TLR2 gene transcription levels in glial cells infected with BS26 peaked at 8 h post-infection." (PMID 37111486, 2023). "In fact, TLR2 blockade and TLR3/7 knockdown stimulated T. cruzi growth, suggesting that these molecules play a significant role in the host cell response to infection." (PMID 37799608, 2023). "The results showed that PRRs such as TLR2 and NLRC3.16 were highly expressed at the early infection stage, which mainly distributed in the mucosa layers." (PMID 36974664, 2023). "To test the role of TLRs in mediating PI3K/PTEN signaling in macrophages during Lm infection, we pre-treated WT and Tlr2–/– BMDMs with PI3K and PTEN inhibitors prior to infection with ΔflaA." (PMID 37216395, 2023). "Our results clearly show that cytokine responses of MDMs to live GBS are different from those to purified TLR2 or TLR4 agonists or heat inactivated bacteria, emphasizing the importance of using live bacteria in experimental models of infection." (PMID 38035076, 2023).
infection (continued). "Four groups of mice (wild type/young, wild type/old, TLR2−/−/young, and TLR2−/−/old) were intravenously infected with S. aureus, and the infection course was followed." (PMID 36808423, 2023). "In particular, we found increased TGF-β1, FGF23, NGAL, IL-18, HIF1-α, TLR2, YKL-40, and B2M mRNA levels long-term post MHV-1 infection." (PMID 37626956, 2023). "We observed a higher frequency of mb-TLR2-expressing B cells, CD8+ T cells, and NK cells in the LN at all post-infection time points." (PMID 38140264, 2023). "Immunoblot studies showed an elevation in protein levels of HIF1-α, TLR-2, and EGFR long-term post-MHV-1 infection." (PMID 37626956, 2023). "In TLR2−/− mice infected with the ΔtolC LVS, one mouse succumbed to infection on day 9 p.i., while all other littermates survived." (PMID 37404047, 2023). "In this study, the expression levels of Tlr2 and Tlr4 were significantly upregulated after Pm HN01 and Pm HN02 infection, which was consistent with previous test results of P. multocida infection." (PMID 36838365, 2023). "One study has suggested the infection has up-regulated the human Micro RNA, miR-101-3p and it paired with the 3’ UTR of mRNA of the TLR2 gene to downregulate the TLR2 gene expression and eventually reduced the cytokine secretion." (PMID 38014008, 2023). "In fact, activation of TLR2 and TLR4 by HA has been shown to induce antimicrobial peptides and help protect vaginal tissue from infection." (PMID 37549960, 2023). "No increase was observed in the transcription of Toll-like receptors (TLR2, TLR4, TLR6) and TLR adaptor protein MYD88 during infection with any of the examined S. suis strains." (PMID 38276150, 2023). "It was shown that TLR2 and TLR4 colocalize with MTs in dendritic cells and the disruption of MTs leads to reduced cytokine production upon infection, suggesting these TLRs are transported in an MT-dependent manner during infection." (PMID 35632720, 2022). "In Leptospira, it has been proven that the LipL32 stimulated inflammatory responses through TLR2 and the calcium-binding cluster (including Asp132, Thr133, Asp164, Asp165, and Tyr178) of LipL32 that could regulate the affinity of LipL32 and TLR2 upon infection of Leptospira." (PMID 35323775, 2022). "We found that the recruited macrophages were fewer in numbers in the tlr2 mutants upon Mma20 and MAC 101 infection compared with wild type controls (–C)." (PMID 36741407, 2022). "R-LD infection results in the NF-κB activation via ligation with TLR2/TLR6, leading to up-regulation of miR-466i in the initial hours of infection, whereas inducing high amounts of IL-10 in late hours." (PMID 35925884, 2022). "Keratinocytes infected with S. schenckii conidia showed an overexpression of the MR, TLR2, CR3, and TLR6 receptors starting 2 h post-infection for a maximum of 10 h, compared to the control group." (PMID 35628694, 2022). "Conversely, after in vitro infection of alveolar epithelial cells by M. bovis BCG, the recruitment of neutrophils was significantly reduced by blocking TLR2." (PMID 35205112, 2022). "In an in vivo infection study, TLR2 was markedly downregulated in response to MAP in PBMC from cattle experimentally inoculated with MAP, indicating a role for TLR2 in the pathogenesis of paratuberculosis." (PMID 36295826, 2022). "Toll-like receptor 2 (TLR2) plays a crucial role in bacterial recognition and the host immune response during infection." (PMID 36142648, 2022). "For instance, infection of mouse bone marrow-derived macrophages (BMDM) with H. pylori stimulates the production of interleukin-6 (IL-6) and IL-1β via TLR2, IL-12, and IL-10 through the TLR4 pathways." (PMID 36317079, 2022). "Most importantly, this review explores and discusses the significance of TLR2 and TLR9 as a crucial factor in determining infection outcome across Leishmania species." (PMID 35119120, 2022).
infection (continued). "Furthermore, L. monocytogenes infection caused the increased expression of CCN1 and the activation of TLR2/4 signaling pathways, and the interaction between these occurred after infection, which may be the reason for the increase in pro-inflammatory cytokines secretion." (PMID 35269881, 2022). "SS1 strain infection induced TLR6 mRNA transcript up to 8.2-fold (P < 0.0001); however, the changes in expression levels of TLR1 and TLR2 were either insignificant or scarcely downregulated." (PMID 36317079, 2022). "Upon infection with H. pylori J99 strain, we noted that TLR1, TLR2, and TLR6 mRNA transcripts were merely upregulated by approximately 2-fold." (PMID 36317079, 2022). "This suggests that in addition to NS1, which is produced post-infection, DENV contains ligands present in the envelope that activate TLR2." (PMID 36680092, 2022). "The levels of expression of TLR1, TLR2, TLR3, TLR6, and TLR9 by pbMECs increase after infection by Mycoplasma bovis." (PMID 36341445, 2022). "Taken together, these data confirm that endosomal TLR2, TLR7 and MyD88 colocalize to Bb-containing phagosomes to facilitate recognition of bacterial ligands and early response to infection." (PMID 34000990, 2021). "In contrast, TLR2-/- mice infected with a ΔbmfBB mutant had CFU and cytokine levels that closely resembled infection of WT mice with WT S. aureus after 72 hours." (PMID 34496007, 2021). "The infection leads to the proliferation and differentiation of CD4+CD25+Foxp3+ Tregs via the activation of the TLR2 pathway." (PMID 34222495, 2021). "Human peripheral monocytes from L. braziliensis-infected patients with CL exhibited higher expression of TLR2, TLR4, TNF-α and IL-10 upon infection in vitro with L. braziliensis." (PMID 33924130, 2021). "Our results demonstrating an interaction between TLR2 and PDIM or ESX-1 for infection outcome suggest that undermining this second component contributes to Mtb’s success as a pathogen." (PMID 34755600, 2021). "In TLR2−/− mice, the pyrolysis-related proteins (GSDMD, IL-1α, and IL-1β) upregulated, which showed the immunocompetence in the infection of A. fumigatus." (PMID 34222495, 2021). "L. rhamnosus L8020 treatment significantly reduced the expression levels of Dectin-2 and CCL2, and tended to reduce the expression levels of TLR2 and CXCL1/KC, following infection by C. albicans GDH18." (PMID 33919079, 2021). "The expression of TLR2 and TLR4 receptors was evaluated in monocytes from CL patients and cells from HS after in vitro infection with L. braziliensis promastigotes." (PMID 34691019, 2021). "The model was based on experimental data obtained from the literature as well as our predictions, which further depicted the role of TLR2 and IL6 signaling pathways during the early stage of infection." (PMID 35011356, 2021). "Because the magnitude of the effect of the gene KO was comparable across these four TLRs, we posit that TLR2, TLR3, TLR4, and TLR5 are equally important in the macrophage response to L. pneumophila at least at the early stages of infection." (PMID 34280250, 2021). "We found that the mutants elicited markedly enhanced expression of a cluster of inflammatory genes induced late after infection; expression was strictly dependent upon MYD88 and TLR2." (PMID 34755600, 2021). "HEK‐Blue cells expressing either TLR2, 4, 7, 8, 9 or NOD2 receptors were stimulated with an increasing number of 6571 MVs per cell, or ‘multiplicity of infection’ (MOI)." (PMID 33815695, 2021). "The frequency of L. braziliensis-infected cells and numbers of intracellular parasites were quantified in TLR2- and/or TLR4-neutralized monocytes from CL patients and HS at 2 and 48 hours post-infection." (PMID 34691019, 2021). "Compatible with the behavior of the MyD88 KO, TLR2 and TLR5 proved important for both IL-6 and TNFα secretion following infection with L. pneumophila." (PMID 34280250, 2021).